CCNE1 (cyclin E1)
Diseases named in the same sentence as CCNE1 in open-access papers (continued):
Sharing a sentence is not in itself a finding about the gene and the disease.
prostate carcinoma (25 papers, 2012 to 2025). A carcinoma that arises from epithelial cells of the prostate gland. "Our analyses showed that in primary tumor CNV in CCNE1 is associated with presence of incidental prostate cancer." (PMID 33298978, 2020). "Downregulation of cyclin D1 and cyclin E1 has also been involved in the G2/M arrest of prostate cancer cell lines C4-2B and DU145 induced by resveratrol combined with docetaxel." (PMID 34513690, 2021). "Here, our study shows that OTUB1 deubiquitinates and stabilizes Cyclin E1 to promote the progression, migration, and proliferation of prostate cancer." (PMID 33537306, 2020). "The results of RO-3306 treatment are the direct evidence of targeting OTUB1/Cyclin E1 axis for prostate cancer." (PMID 33537306, 2020). "To identify the possibility of targeting prostate cancer with OTUB1/Cyclin E1 axis, we treated PC3 cell with RO-3306, a Cyclin E1/CDK2 related inhibitor, in the range dose of 0, 340 nM, 1 uM, 2 uM, 3 uM, and 5 uM." (PMID 33537306, 2020). "SPOP directly interacts with CYCLIN E1 and specific regulates its stability in prostate cancer cell lines." (PMID 30237511, 2019). "CYCLIN E1 expression rescued proliferation, migration, and tumor formation of prostate cancer cell suppressed by SPOP." (PMID 30237511, 2019). "These suggest that SPOP mutants in prostate cancer have less activity to promote CYCLIN E1 degradation." (PMID 30237511, 2019). "PKMYT1 promoted the growth of cells by targeting CCNB1 and CCNE1 in prostate cancer." (PMID 36793346, 2022). "Interfering with the contact between OTUB1 and Cyclin E1 might provide a potential therapy for prostate cancer." (PMID 33537306, 2020). "So far, we have a lot of evidence to identify the hypothesis that OTUB1 promotes the progression and proliferation of prostate cancer via mediating and stabling Cyclin E1." (PMID 33537306, 2020). "The OTUB1/Cyclin E1 axis may serve as a potential therapeutic target for patients with prostate cancer." (PMID 33537306, 2020). "Furthermore, in silico analysis shows that one of the target genes of miR-151b, CCNE1, is involved in T-cell signaling, cell-cycle, DNA-damage induced signaling and breast, pancreas, lung and prostate cancer pathways." (PMID 29682178, 2018). "Upregulation of cyclin E1 levels by hypoxia has been observed in prostate cancer cells." (PMID 29426911, 2018). "miR-3648 facilitates prostate cancer cell proliferation by inhibiting APC2, which leads to the activation of the Wnt/β-catenin pathway by increasing cyclin D1 and cyclin E1 expression and decreasing p21 expression." (PMID 35037826, 2022). "Although our research found that the deubiquitinase OTUB1 promotes the stability of Cyclin E1 and the progression of prostate cancer, the specific mechanism of OTUB1 mediated function of Cyclin E1 remains to be further studied." (PMID 33537306, 2020). "These represented cell cycle/mitosis; among others CCNE1, CCNE2, CCNG2, CCNL1, CCNT1, CDK12 and CDKN3, prostate cancer; including the androgen receptor (AR), metabolism as well as targets of the transcription factors E2F, AP2, SP1, ETF and Pax3." (PMID 26698305, 2015). "TTK may inhibit the proliferation of prostate cancer and the progression of prostate cancer by inhibiting the expression of CDK2 and CCNE1 complex." (PMID 37682152, 2023). "In prostate cancer, OTUB1 can block the ubiquitination of cyclin E1 and keep it stable." (PMID 34773364, 2021). "The prognosis of patients with prostate cancer may be improved when the connection between OTUB1 and Cyclin E1 are interrupted or disturbed." (PMID 33537306, 2020). "The results further illustrated that OTUB1 regulated the expression and function of Cyclin E1 in vivo, and targeting OTUB1/Cyclin E1 axis might provide a potential therapeutic method for these patients with prostate cancer." (PMID 33537306, 2020). "MiR-195-5p has been identified to interact with NOB1, NOTCH2 and CCNE1 in several cancers, while miR-195-5p has not been investigated in prostate cancer." (PMID 32440687, 2020).
colorectal cancer (23 papers, 2007 to 2025). A primary or metastatic malignant neoplasm that affects the colon or rectum. "As previously reported, CCNE1 amplification was detected in colorectal cancer patients and both increased and decreased expression of CCNE1 were found to be associated with drug resistance in colon cancer, depending on the therapeutics used." (PMID 37751451, 2023). "Some studies have consistently shown that CCNE1 is associated with disease progression in various malignancies and is clinically associated with poor prognosis in patients with ovarian, breast, bladder and colorectal cancer." (PMID 34980127, 2022). "Additionally, it was also shown through the use of genetic rescue experiments that the aberrant increases in Cyclin E1 observed following FBXW7 inactivation in colorectal cancer cells were an underlying mechanism driving increases in CIN." (PMID 35008511, 2021). "Our results demonstrated that roburic acid effectively suppressed colorectal cancer cell proliferation by inducing G0/G1 cell cycle arrest and downregulating the protein expression of Cyclin B1, Cyclin D1, and Cyclin E1." (PMID 35222445, 2022). "On the other hand, METTL3 stabilizes its expression level by methylating the m6A site of the CCNE1 3′UTR mRNA to increase the expression of the cyclin E1 to promote colorectal cancer cell proliferation." (PMID 35614935, 2022). "Given the established role of cyclin-dependent kinases (CDKs) and cyclins in cell cycle regulation, we examined the expression of cyclin D1, cyclin E1, and CDK6 in colorectal cancer cells treated with CS&Z extract." (PMID 40429805, 2025). "miR‐424‐5p was shown to promote proliferation and metastasis of colorectal cancer cells by targeting SCN4B and also to inhibit cell proliferation by targeting E2F7, Cyclin E1, Cyclin A2, and Cyclin D1." (PMID 40405535, 2025). "Several genes with high-frequency and important CNVs, namely, MYC, FGFR1, CCNE1, and CCND3 have been observed in lung and colorectal cancer samples." (PMID 35402275, 2022). "The results revealed dose-dependent and time-dependent reductions in the expression of a range of cell cycle proteins, including cyclin E1, cyclin D1, and CDK6, accordingly indicating that CS&Z can influence the progression of the cell cycle in colorectal cancer cells." (PMID 40429805, 2025). "Moreover, another study on colorectal cancer found that ZC3H13 inhibits tumor cell proliferation and invasion by downregulating the expression of Snail, cyclin D1 and cyclin E1 by inhibiting the RAS signaling pathway." (PMID 35223847, 2022). "Consistently, CCNA2, CCNB1, CCND1, and CCNF have been observed to be upregulated in colorectal cancer, but there is no clear evidence that CCNE1 and CCNJL are also differentially expressed between colon tumor and normal tissues." (PMID 33996604, 2021). "MiR-103b has been shown to target several molecules which play a role in carcinogenesis in other cell types, for example CCNE1, CDK2, CREB1, DICER, and PTEN, and colorectal cancer cell line studies indicate dysregulation of miR-103b expression can drive cancer progression." (PMID 29141625, 2017).
liver cancer (22 papers, 2009 to 2025). An epithelial or non-epithelial malignant neoplasm that arises from the liver. "CCNE1 overexpression is linked to the initiation of liver cancer and dismal prognosis in patients suffering from HCC." (PMID 34692847, 2021). "Ccne1 overexpression cause liver tumor development in mice, Cdk2 plays a key role in cell cycle progression in hepatocyte, and cyclin-dependent kinase 1 (Cdk1) is essential for cell division of liver cancer." (PMID 32570707, 2020). "For example, reduction of CCNE1 with siRNA causes cell cycle arrest in liver cancer cell lines." (PMID 19688090, 2009). "The results of the two apoptosis detection experiments showed that CCNE1 overexpression reverses the influence of SCUBE3 knockdown on the apoptosis of liver cancer cells." (PMID 34980127, 2022). "To verify how SCUBE3 promotes the proliferation of liver cancer cells through CCNE1, we first applied KEGG enrichment analysis on the DEGs in the classical pathway screened by Affymetrix GeneChip microarray analysis." (PMID 34980127, 2022). "We also found that the use of RNA interference to target CCNE1 inhibits the neoplastic growth of a wide variety of liver cancers." (PMID 34980127, 2022). "Therapeutic inhibition of CCNE1 in the course of liver cancer progression significantly reduces tumour burden and should therefore be considered as a beneficial treatment option against HCC." (PMID 34830835, 2021). "Interventional depletion of Cyclin E1 in the course of liver cancer progression significantly reduces tumour burden." (PMID 34830835, 2021). "The amplification of CCNE1 in this pathway is significantly related to the metastasis of liver cancer, which has been identified as an important target for tumor cells." (PMID 32963562, 2020). "Contrary to CCNA2 alterations that seem to be specific of liver cancers, CCNE1 activation by high-level amplification is frequent across human cancers, in particular in gynecologic cancers." (PMID 30531861, 2018). "In order to test whether the pro-fibrotic function of Ccne1 in HSCs, as identified above, may also trigger the formation of liver cancer, we applied the N-nitrosodiethylamine (DEN)/CCl4 model." (PMID 37620309, 2023). "Thus, CCNE1 expression has a particular relationship with the occurrence and development of liver cancer." (PMID 34980127, 2022). "Therefore, the accumulation of CCNE1 eventually promotes the transformation of liver cancer cells from the G1 phase to the S phase, promoting the proliferation of liver cancer cells." (PMID 34980127, 2022). "Furthermore, increased CBX7 greatly reduced tumour proliferation as measured by PCNA, and one CBX7 target, cyclin E1, which is essential for liver cancer progression, was significantly reduced upon increased CBX7 expression." (PMID 35867177, 2022). "Therefore, interventional inactivation of CCNE1 represents a promising strategy the treatment of liver cancer." (PMID 34830835, 2021). "Thus, specific inhibition of Cyclin E1 expression represents a promising strategy for the treatment of liver cancer." (PMID 34830835, 2021). "For example, in liver cancer, TFDP1 overexpression promotes cell proliferation by upregulating cyclin E1 (CCNE1)." (PMID 41458288, 2025). "These three liver cancer cases were also infected with either HBV or HCV, and the AAV2 integration sites were located at MLL4, CCNE1, and an intergenic region of chromosome 5, respectively." (PMID 30521023, 2018). "The expression of CCNE1 was not correlated with the sex of the patients, i.e., CCNE1 expression in liver cancer tissues of female patients was not significantly different from that in liver cancer tissues of male patients." (PMID 34980127, 2022). "The relationship between CCNE1 expression and sex, body weight, and race, but not liver cancer grade, of liver cancer patients, significantly affected the overall survival rate of these patients." (PMID 34980127, 2022).
liver cancer (continued). "Together, these results suggest that CCNE1 is involved in dedifferentiation and acquisition of invasive features of liver cancer cells independent of CDK2." (PMID 34830835, 2021). "However, unlike the cyclin E1 proteins, in vitro studies showed that cyclin E2 is not essential for initiating liver cancer." (PMID 38981878, 2024). "Finally, we aimed to analyse whether our findings regarding CCNE1 and CDK2 in murine liver cancer can also basically be found in HCC patients." (PMID 34830835, 2021). "However, enhanced polyploidy due to deregulated cell cycle proteins is not necessarily protective as mice overexpressing CCNE1 show strong hyperpolyploidization but develop spontaneous liver cancer." (PMID 33225610, 2020).
pancreatic cancer (19 papers, 2010 to 2025). "LRH-1 expression is elevated in pancreatic cancer and promotes pancreatic cancer cell growth through stimulation of cyclin D1, cyclin E1 and c-Myc, while genome-wide association studies implicate mutations in the LRH-1 gene in pancreatic ductal adenocarcinoma." (PMID 24049078, 2013). "Further, NR5A2 expression is elevated in pancreatic cancer andpromotes pancreatic cancer cell growth through stimulation of cyclin D1, cyclin E1 and c-Myc, while genome-wide association studies implicate mutations in the NR5A2 gene in pancreatic ductal adenocarcinoma." (PMID 25514243, 2014). "Due to the amplification of acquired CCNE1 in breast and pancreatic cancers, the cells have acquired resistance to CDK4/6 inhibitors in vitro, damaging the sensitivity of cells to CDK4/6 inhibitors but still rendering them sensitive to CDK2 inhibitors." (PMID 39648148, 2024). "Further, β-catenin activation induced by CCR9 increased the expression of Cyclin E1, Cyclin D1, and E-Cadherin to increase the lethal dose of gemcitabine in pancreatic cancer, suggesting that CCR9/β-catenin signaling enhances pancreatic cancer chemoresistance." (PMID 26879872, 2016). "The expression of NR5A2 is also elevated in pancreatic cancer and promotes pancreatic cancer cell growth through stimulation of cyclin D1, cyclin E1 and c-Myc." (PMID 25514243, 2014). "Based on data that has attributed cellular functions to fibroblast proliferation in other tissues, we investigated a panel of ten central regulators of cell proliferation (c-Myc, Cyclin D1, Cyclin E1, FGF2, FGFR2, EGFR, EGF, FGF1, FGFR1 and VEGFA) in pancreatic cancer-associated fibroblasts (CAFs)." (PMID 38678032, 2024). "Indeed, chemotherapy-induced resistance via CDK4 amplification, RB loss, and cyclin E1 amplification has been suggested to contribute to the lack of efficacy of palbociclib in pancreatic cancer when given as the third or fourth line of treatment." (PMID 36970055, 2022). "Studies on the therapeutic efficacy of PRI-724/ICG-001 in pancreatic cancer have revealed one potential mechanism that Wnt/β-catenin-dependent inhibition of cell proliferation was partially due to downregulation of various genes that are involved in cell cycle, e.g. CCNE1, E2, and A2." (PMID 30613366, 2018). "Next, we explored correlation between E2F4, CCNE1, CCND1 and NOP14 in pancreatic cancer tissue in TCGA database." (PMID 37506248, 2023). "The present paper reported that, in pancreatic cancer (PC) cells, E2F1, CCND1, CCNE1, and all members of the MCM2-7 family were downregulated after inhibition of the RPL21 expression, leading to the reduction of DNA replication." (PMID 33014855, 2020). "Cyclin E1, epithelial growth factor (EGF), IL-6, CXCL8, IL-10, and IL-1RA have all been shown to be elevated in individuals with pancreatic cancer and high IL-6 or IL-10 levels correlated to poor survival." (PMID 20214814, 2010).
cervical cancer (17 papers, 2016 to 2025). A primary or metastatic malignant neoplasm involving the cervix. "Prior studies in gastric, lung, and cervical cancers have suggested that ASF1B modulates cell cycle regulators such as Cyclin E1, CDK2, and MYC, consistent with our enrichment results showing associations with DNA replication and mitotic pathways." (PMID 40944429, 2025). "In cervical cancer patients, CCNE1 amplification occurred in 0.69% of squamous cell carcinomas (SCC, 3/434) and 0.91% of adenocarcinomas (ADC, 3/331), with no amplification detected in adenosquamous carcinomas (0/51)." (PMID 41331376, 2025). "For example, targeting of CCNE1 by miR-497 to suppress cervical cancer cell proliferation is reported." (PMID 39095857, 2024). "Functional studies showed that CCNE1 play critical roles in cervical cancer cell growth and cell cycle transition from G1to S phase." (PMID 32818316, 2020). "Functionally, we showed that lnc_000231 promotes cervical cancer cells proliferation and tumour formation by acting as miR‐497‐5p sponge and maintaining cyclin E1 (CCNE1) expression." (PMID 32818316, 2020). "Results showed that CCNE1 was highly expressed in cervical cancer cells than normal cervical epithelial cell line." (PMID 32818316, 2020). "In vitro and in vivo results showed that lnc_000231 promotes cervical cancer cell proliferation and tumour formation by acting as miR‐497‐5p sponge and maintaining cyclin E1 (CCNE1) expression." (PMID 32818316, 2020). "In the meantime, we showed that lnc_000231 plays a critical role in cervical cancer progression by acting as miR‐497‐5p sponge and maintain CCNE1 expression." (PMID 32818316, 2020). "E6 hijacked KDM5C/lnc_000231/miR‐497‐5p/CCNE1 signalling pathway is a promising target for cervical cancer treatment in the future." (PMID 32818316, 2020). "E6 hijacked KDM5C/lnc_000231/miR‐497‐5p/CCNE1 signalling pathway is promising targets for cervical cancer treatment in the future." (PMID 32818316, 2020). "In cervical cancer, CCNE1 amplification may contribute to early epithelial transformation, potentially enhancing proliferative signaling in HPV-infected cells." (PMID 41331376, 2025). "CCNE1 gene was targeted by miR-16-1 in Cervical Cancer cells." (PMID 35057823, 2022). "Besides, the expression of CDK2 and cyclin E1 increased in cervical cancer compared with adjacent normal tissues." (PMID 33516252, 2021). "In this study, we found that CCNE1 is up‐regulated in cervical cancer cells." (PMID 32818316, 2020). "As a cell cycle regulator, the roles of CCNE1 in cervical cancer were also investigated." (PMID 32818316, 2020). "Overexpressing miR‐497‐5p greatly down‐regulated CCNE1 expression in cervical cancer cells." (PMID 32818316, 2020). "In addition, miR-497 can inhibit the proliferation of cervical cancer cells by acting on cyclin E1." (PMID 27764149, 2016). "The mRNA expression levels of CCND1, CCNE1, CDK2, CDK6, and p21CIP1 were significantly related to the histological classification of cervical cancer (p < 0.05)." (PMID 35246013, 2022). "Polydatin efficiently inhibited cervical cancer cell proliferation by regulating cell cycle-related proteins including p21, p27, CDK2, CDK4, Cyclin D1, and Cyclin E1." (PMID 33912552, 2021). "Besides, circZFR bound with SSBP1, thereby inducing the assembly of CDK2/cyclin E1 complexes, which induced p-Rb phosphorylation, thus releasing activated E2F1 leading to cell cycle progression and cell proliferation in cervical cancer." (PMID 36008845, 2022). "Furthermore, consistent with the fact that p21 is a cyclin-dependent kinase inhibitor, we found that levels of cyclin-related proteins such as Cyclin D1, Cyclin E1, CDK2 and CDK4 were reduced in cervical cancer cells overexpressed by ST3Gal IV." (PMID 33598419, 2020).